HGF (hepatocyte growth factor)
Diseases named in the same sentence as HGF in open-access papers (continued):
Sharing a sentence is not in itself a finding about the gene and the disease.
cancer (continued). "A number of recent studies have shown that the hepatocyte growth factor (HGF) and its receptor Mesenchymal epithelial transition factor (c-MET) influence the growth, survival, angiogenesis, and metastasis of cancer cells." (PMID 36034555, 2022). "HGF/c-MET-induced up-regulation of circCCDC66 expression promoted enrichment of renal cancer stem cells and accelerated the malignant process of cancer." (PMID 36698408, 2022). "EGCG blocked HGF-induced cell growth and invasion via repression of HGF/c-Met signaling in SCC VII/SF cells, whereas it blocked xenograft cancer survival in vivo by increasing cell death." (PMID 35402265, 2022). "The HGF/c-MET axis is activated in cells with increased HGF and c-MET expression, promoting cell proliferation, motility, angiogenesis, and epithelial-to-mesenchymal transition (EMT), ultimately leading to cancer cell growth and metastasis." (PMID 35630066, 2022). "Combined with previous eQTL analyses, we found nine eQTLs, including nine eVariants and two eGenes (HGF and FCER1G), that correlated with the survival of cancer patients." (PMID 35204406, 2022). "C-Met is a tyrosine kinase receptor for the hepatocyte growth factor (HGF) ligand and is highly activated in several human cancers, affecting several key cancer-signaling pathways." (PMID 34577547, 2021). "Growth factor HGF/SF binds and activates MET, normal activation induces embryogenesis, while abnormal activation of MET in cancer leads rapid progression by activating multiple signaling pathways including Ras, PI3K, STAT, Wnt, and Notch signaling pathway." (PMID 34262595, 2021). "CAFs have been reported to be involved in cancer progression through the secretion of growth or pro-inflammatory factors, such as transforming growth factor-β (TGF-β), hepatocyte growth factor (HGF), and C–X–C motif chemokine ligand 12(CXCL12)." (PMID 34284780, 2021). "To date, the limited evidence on HGF, EGF, and IGF-1 and their effect on liver regeneration seems to support a beneficial effect on the regeneration process or in cancer recurrence." (PMID 34572344, 2021). "The translocated EGFR suppresses miR‐26a/b expression in the liver stromal cells and activates the secretion of hepatocyte growth factor (HGF), which ultimately binds to the c‐MET receptor on the DTCs, promoting cancer proliferation in vitro and in vivo." (PMID 34295457, 2021). "Transforming growth factor-β (TGF-β) and hepatocyte growth factor (HGF) derived from CAFs promote the EMT and metastasis of cancer cells." (PMID 34631221, 2021). "Since treatment of the co-culture with either RSV or antibodies specifically against HGF abolished stroma-enhanced migration to a similar degree, the authors proposed that RSV inhibits cancer cell migration by counteracting the stromal cell–derived HGF." (PMID 33535458, 2021). "MET is a receptor tyrosine kinase (RTK) that, when bound by its ligand hepatocyte growth factor (HGF), coordinates a programme of invasive growth that broadly overlaps with the process of EMT, both in cancer and during the physiological process in development." (PMID 33772015, 2021). "Markedly upregulated Hpse levels trigger the MMP-9, hepatocyte growth factor (HGF) and vascular endothelial growth factor (VEGF) expression, thereby leading to cancer progression." (PMID 34156395, 2021). "IL-1α-activated PSC can assist cancer cell migration, which is known to be inhibited by TGF-β via blocking IL-1α-mediated secretion of hepatocyte growth factor and reducing IL-1 receptor expression." (PMID 34988078, 2021). "Hepatocyte growth factor activator (HGFAC), an activator of hepatocyte growth factor (HGF), has been previously reported to be involved in liver regeneration in response to injury and several types of cancers." (PMID 33879119, 2021). "Treating tumors with the combination of HGF and anti-IFN-γ agents restored the expression of SLC3A2 and SLC7A11, which suggested that the positive role of IFN-γ in cancer cellular ferroptosis." (PMID 34593794, 2021).
cancer (continued). "Some of these potentially metastatic CAF-secreted factors involved in EMT have been studied extensively in the past years in multiple cancer types, such as interleukin-6 (IL-6), osteopontin (OPN), hepatocyte growth factor (HGF), and CXCL12." (PMID 34572947, 2021). "In HCC, as in other types of cancer, VEGF shares common pathways with EGF, IGF-1, and HGF, such as MET, EKT, or Akt, among others." (PMID 34572344, 2021). "Neutrophils can directly induce proliferation of cancer cells through the secretion of NE, S100A4, S100A8/A9, FGF2, HGF, BMP2, TGFβ2 and transferrin." (PMID 34572138, 2021). "The list of mediators, including TGF-β1, HGF, GRO-1, and IGF-1, depends on cancer and normal cell types." (PMID 33921783, 2021). "Blocking of the HGF/MET axis by the Combo treatment was extremely specific, with untreated and Combo-treated cancer cells giving rise to a superimposable expression profile." (PMID 34298732, 2021). "OC treatment not only affected cells grown in monolayers, but it has been demonstrated that at a dose of 20 μM it inhibited the growth of HGF-induced 3D spheroids of human breast MDA-MB-231 cancer cells and human prostate DU145 cancer cells." (PMID 33513799, 2021). "Hepatocyte growth factor (HGF) and its receptor C-met play a critical role in cancer development and progression." (PMID 34050266, 2021). "Proliferative activity is a vital component of cancer development and progression, with the MET/HGF axis being a known molecular regulator." (PMID 33526881, 2021). "CAF secrete growth factors and cytokines such as transforming growth factor- β (TGF- β), platelet derived growth factor (PDGF), hepatocyte growth factor (HGF), and vascular endothelial growth factor (VEGF) that modify the TME and enhance cancer cell growth." (PMID 34071280, 2021). "Our first challenge was to distinguish between HGF/c-MET-activated and -inactivated samples within the 11 different cancers." (PMID 34261467, 2021). "KEGG analysis identified adhesion, hematopoiesis and cancer-related proteoglycans as affected pathways (e.g. metformin: CD9, CTSL, IL5, HGF; insulin: EGF, EZR, PLCG2, TFRC)." (PMID 33690729, 2021). "This study is believed to provide general understanding of apoptotic mechanisms of HGF knockout in HCC and give an idea as a candidate in developing anti-cancer therapies." (PMID 34683124, 2021). "This leads to an increased HGF production by CAFs, which in turn activates MET in cancer cells, hence the diminished inhibitory effect of TKIs." (PMID 33673405, 2021). "In this study, we conducted cell migration and invasion assays under serum-free conditions, using GAS6 or HGF as chemoattractants to dissect the roles of AXL and MET in cabozantinib-mediated inhibition of cancer cell migration and invasion." (PMID 32055714, 2020). "SPINT2 gene expression was down-regulated, altering dysregulation of the HGF/MET signaling pathway, which contributes to cancer development and progression." (PMID 32256213, 2020). "Though HGF/c-MET signalling plays an important role in embryonic development and wound healing, this pathway is rarely active in adults apart from malignancies." (PMID 33271944, 2020). "MET is the receptor of hepatocyte growth factor (HGF), and a well-known RTK being developed as an anti-cancer target." (PMID 33176788, 2020). "Since the HGF/MET axis plays an important role in cancer, various approaches have been explored to inhibit it, including the use of MET-neutralizing antibodies, HGF antagonists, and tyrosine kinase activity-targeted inhibitors (TKIs)." (PMID 32435640, 2020). "The hepatocyte growth factor (HGF)/c-MET pathway is upregulated in PC and mediates the interaction between cancer cells and stromal pancreatic stellate cells (PSCs)." (PMID 32203220, 2020). "Growth factor sequestration by IGFBP-3-Fc enhances the activity of EGFR inhibitors by decreasing cell survival and inhibiting bFGF, HGF, and IGF1 growth factor rescue and also potentiates the activity of other cancer drugs." (PMID 32066763, 2020).
cancer (continued). "Cancer cell migration and invasion has been augmented by other CAF-derived factors such as HGF, FGF-2, and IL-8." (PMID 33050237, 2020). "HGF binds to the receptor MET and induces several biological activities involved in cancer progression, such as growth, survival, motility, and metastasis." (PMID 33066121, 2020). "Because of the significance and importance of the HGF/MET signaling pathway, more research is needed here to clarify the connections to normal development as well as cancer growth and proliferation." (PMID 33066121, 2020). "We have previously reported that hWJSC-CM contains significantly higher levels of interleukins and adhesion molecules like IL-1a, IL-6, IL-8, HGF, SCF, and MCP-1 that regulate cancer cell death and modulate the immune system." (PMID 32377203, 2020). "In conclusion, our research revealed a novel mechanism between hepatocyte growth factor/c-Met/cir-CCDC66 and cancer stem cell enrichment." (PMID 31994979, 2020). "Cancer cell functions such as migration, stemness and EMT were assessed in the collagen matrices upon exposure to HGF-neutralising antibody (Hi), or c-MET inhibitor (Ci) alone or in combination for longer periods of 4 weeks." (PMID 32203220, 2020). "In our study, we analyzed the Cancer Cell Line Encyclopedia (CCLE), The Cancer Genome Atlas (TCGA), and the Genomics of Drug Sensitivity in Cancer (GDSC) database, to select six genes (FBN1, FN1, HGF, MMP9, THBS1, and VCAN) as target genes." (PMID 33014013, 2020). "MET inhibitors inhibit proliferation, invasion, migration, and HGF/MET downstream signaling in gastric MET-amplified cancer cells, but HGF overexpression in cancer cells impairs this phenomenon." (PMID 32435640, 2020). "CAF secretion of growth factors such as EGF, FGF, HGF, TGF-β, and cytokines such as IL6 facilitates the migration of cancer cells and confers resistance to antitumor therapy." (PMID 33072555, 2020). "Considering the critical role played by the HGF–MET axis in myocardial protection, a warning should be given about the possible cardiac side effects of the cancer target therapies." (PMID 32133617, 2020). "The signaling of the HGF/SF/MET system plays a crucial role in the regeneration of several tissues such as the liver or the skin, while its deregulation is often observed in cancer." (PMID 32444769, 2020). "The HGF/c-MET pathway that mediates cross-talk between pancreatic stellate cells (the main collagen producing stromal cells) and cancer cells, as well as between PSCs and endothelial cells, is a potentially useful target for therapy." (PMID 33271944, 2020). "CSCs secrete various cytokines and ligands, such as such as hepatocyte growth factor (HGF) and CCL2, to reprogram normal fibroblasts into CAFs, thereby contributing to cancer cell stemness." (PMID 32754274, 2020). "Our results revealed that GAS6 and HGF had an additive effect on cell migration, suggesting that cancer progression is promoted by various humoral factors such as GAS6 and HGF in the TME." (PMID 32055714, 2020). "The results of Boyden chamber assays showed that cancer cell migration was induced by GAS6 and HGF in SKOV3 cells in serum-free medium." (PMID 32055714, 2020). "The signaling in several types of cancer cells is sustained by adipokines secreted by adipocytes, mainly including leptin, adiponectin, oestrogens, insulin-like growth factor 1 (IGF-1) and hepatocyte growth factor (HGF)." (PMID 32854444, 2020). "Our in vitro 3D culture studies supported our in vivo observations for HGF + c-MET inhibition on EMT, with cancer cells expressing a significant increase in E-cadherin and a significant decrease in vimentin in this treatment group." (PMID 32203220, 2020). "Surprisingly, and in contrast to the lack of effect on metastasis in vivo, we found that inhibition of both HGF and c-MET (over a period of 4 weeks in culture) significantly decreased the invasion of cancer cells into the collagen matrices." (PMID 32203220, 2020).
cancer (continued). "Hepatocyte growth factor (HGF), which promotes various cancer cell metastasis, triggered cancer cell migration and invasion via cMet-ERK-COX2 and MAPK signaling pathways." (PMID 32581782, 2020). "Co-culturing GC cells with bone-marrow-derived myofibroblasts (BMFs) has shown high expression of IL-6 and hepatocyte growth factor (HGF) secreted by BMFs, which mediated the secretion of TGF-β1 by the surrounding cancer cells." (PMID 32268527, 2020). "In liver cancer, HGF/MET pathway activation provokes the Warburg effect and glutaminolysis, mediating cancer cell development." (PMID 33194736, 2020). "Several CAF-derived soluble factors, such as HGF, Wnt, and PDGF also contribute to EMT phenotype acquisition in cancer cells." (PMID 33050237, 2020). "It functions as a co-receptor for semaphorins and for multiple growth factors including VEGF, TGF-β, EGF, FGF, HGF and PDGF, resulting in versatile and diverse biological roles encompassing axon guidance, angiogenesis, wound healing, cancer and immunity." (PMID 31208428, 2019). "A previous study revealed that HGF induced EMT in HCC cells 19 and EMT was found to play a critical role in cancer drug resistance 8, 9; thus, we focused on EMT in the present study." (PMID 30761258, 2019). "We have recently found that in various cancer cells, MET can be induced to form clusters on the plasma membrane in response to its natural ligand HGF stimulation." (PMID 30760737, 2019). "In this study, it was found that both miR-1-3p and miR-206 target c-MET, a receptor for HGF, thus impairing HGF-induced EMT and improving the efficacy of anti-cancer therapy." (PMID 31861937, 2019). "HGF binds to the HGF receptor c-MET, inducing several biological activities involved in cancer progression." (PMID 31355133, 2019). "Lactate can act as a signaling molecule which instructs cancer associated fibroblasts (CAFs) to produce hepatocyte growth factor (HGF), whose secretion activates MET signaling in cancer cells, overcoming TKI inhibitory effects." (PMID 31795465, 2019). "A previous report revealed that binding of HGF to c-Met triggers receptor homodimerization leading to subsequent promotion of Src/STAT3 signaling and cancer progression." (PMID 30782177, 2019). "Our method can not only prioritize the significant cancer driver genes but also identify some potential cancer driver genes which were neglected by the NCG 4.0 such as the NES, MET and HGF." (PMID 31888619, 2019). "In cancer cells, decorin decreases the expression of VEGFA and HIF-1α through interfering with the signaling pathways of Hepatocyte Growth Factor (HGF/Met) and epidermal growth factor receptor (EGFR)." (PMID 31428311, 2019). "For example, transforming growth factor-beta (TGF-β) and hepatocyte growth factor (HGF) signaling often induces EMT by activating EMT transcription factors and enhances the stemness of cancer cells." (PMID 31861937, 2019). "Recently, aberrant high expression of hepatocyte growth factor (HGF) was found to be closely correlated with EMT and metastasis in various cancers including NSCLC 12-14." (PMID 31602259, 2019). "SCLC is well-known to release growth factors, such as bombesin, gastrin-related peptide (GRP), HGF, VEGF, TGF-β, HGF, and FGF, which have been shown to activate focal adhesion pathways in several cancers." (PMID 31671774, 2019). "In the presence of cancer cells, fibroblasts can be activated by cancer or immune secreted TGF-β, FGF-2, HGF, PDGF, and interleukins, as well as reactive oxygen species to become cancer-associated fibroblasts (CAFs)." (PMID 31075118, 2019). "We focused on four well-established EMT-inducing agents, EGF, HGF, IGF-1, and TGF-β1, whose secretion by the cancer cells was higher than that by the PMCs." (PMID 31086083, 2019). "The hepatocyte growth factor (HGF) and its receptor tyrosine kinase, MET, play key roles in cancer development and progression as a result of their involvement in generating mitogenic, motogenic, and angiogenic activities." (PMID 31072015, 2019).
cancer (continued). "TAMs produce soluble growth factors (i.e., HGF, EGF, TGFβ, PDGF, etc.)and inflammatory cytokines (IL-1β, IL-6, and TNFα) that can induce EMT in cancer cells." (PMID 31772577, 2019). "Similar to our CVL findings, other researchers found significantly increased levels of IL-6, VEGF, HGF and OPN in both cancer patients’ sera and cancerous tissues." (PMID 31089160, 2019). "The CAF-secreted diffusible factors, hepatocyte growth factor (HGF), TGF-β, and basic fibroblast growth factor (bFGF), were shown to mediate the observed increase in cancer cell motility." (PMID 31284458, 2019). "For instance, cancer-associated fibroblasts (CAFs) and mesenchymal stem cells (MSCs) nourish cancer cells by secreting growth factors such as the fibroblast growth factor (FGF) and hepatocyte growth factor (HGF)." (PMID 31480381, 2019). "The HGF-activated c-MET signalling pathway has been extensively studied, especially for its relationship with cancer progression." (PMID 30646583, 2019). "MET, also known as hepatocyte growth factor (HGF) receptor, is a receptor tyrosine kinase that promotes tissue growth in developmental, wound-healing, and cancer metastasis." (PMID 31652258, 2019). "Following HGF treatment, coherent sheets of epithelial NBT-II carcinoma cells progressively dissociated over time, leading to establishment of single mesenchymal-like migratory cells as early as 9 h." (PMID 31554791, 2019). "Therefore, HGF/c-Met could be a potentially useful antiangiogenic target in human cancers." (PMID 29416603, 2018). "MACC1 functions as a key regulator of the HGF/c-MET axis, which is a promising target for cancer therapy." (PMID 29510730, 2018). "Another ECM component that is capable of sequestering HGF is the thrombospondin-1 (TSP-1), a matricellular protein involved in angiogenesis, inflammation and cancer." (PMID 30352967, 2018). "MET and HGF co-targeting has been previously investigated in MET-addicted tumors and in cancers expressing a MET/HGF autocrine loop." (PMID 30544501, 2018). "In cancer tissue, activation of HGF/MET signaling axis occurs mainly by paracrine fashion, and several cancers express HGF, which leads to autocrine-loop-style MET activation." (PMID 30469509, 2018). "As a result, HGF, platelet derived growth factor A and WNT16, reported to be produced by CAFs from other cancer types, are also expressed in GCAFs, which correlate with the poor overall survival." (PMID 30038550, 2018). "In a minority of cancers, the MET gene is reported to act as a driver oncogene; however, the majority of cancers utilize wild-type MET, which relies on HGF, as an expedient to confer a malignant phenotype." (PMID 29890660, 2018). "Although few in vivo studies have been reported on these thus far, literature describes various interesting cancer targets for OC, being the main phenylethanoid studied for both the c-MET and hepatocyte growth factor (HGF)." (PMID 30250008, 2018). "By producing secretory factors such as hepatocyte growth factor (HGF), CAFs remarkably decrease sensitivity of cancer cells to various anticancer agents." (PMID 28929459, 2018). "However, several studies reported that deregulation or improper activation of the HGF/Met signaling pathway can promote cytoskeletal changes, leading to the acceleration of proliferation, angiogenesis, motility, and survival and invasive/metastatic abilities of many cancer cells." (PMID 30250008, 2018). "During cancer progression, MACC1 overexpression should inhibit cancer cell apoptosis and promote cancer cell EMT via HGF/MET pathways." (PMID 30021598, 2018). "Despite advances and improvement in techniques to antagonize HGF/c-MET pathway using small molecule inhibitors, many cancers are unresponsive to these inhibitors due to resistance in clinical research." (PMID 30360560, 2018).